CHD2 (chromodomain helicase DNA binding protein 2)
Diseases named in the same sentence as CHD2 in open-access papers (continued):
Sharing a sentence is not in itself a finding about the gene and the disease.
ovarian carcinoma (2 papers, 2022 to 2025). A malignant neoplasm originating from the surface ovarian epithelium. "Several oncogenes frequently mutated in endometrial and ovarian cancer (ARID1B, ATM, BRCA1, CHD2, POLE, and PMS2) were also present in LMS." (PMID 39691991, 2025). "In this study, further study also demonstrated that HK2 could elevate the expression of EMT-related factors in human ovarian cancer cell, like fibronectin, MMP9, CHD2, Vemintin, ZEB1 and ZEB2." (PMID 35953860, 2022). "Additionally, the positive correlation between HK2 and fibronectin, MMP9, CHD2, Vemintin, ZEB1 and ZEB2 in human ovarian cancer were also confirmed from the GEPIA online database." (PMID 35953860, 2022). "Additionally, the positive correlation between HK2 and fibronectin, MMP9, CHD2, Vimentin, ZEB1 and ZEB2 in human ovarian cancer were confirmed from the GEPIA online database (p < 0.05)." (PMID 35953860, 2022).
Alzheimer disease (1 paper, 2025). A progressive, neurodegenerative disease characterized by loss of function and death of nerve cells in several areas of the brain leading to loss of cognitive function such as memory and language. "Similarly, most brains analyzed harbored a deletion overlapping a dark intronic AluYa5 element within chromodomain helicase DNA binding protein 2 (CHD2) in close proximity to an Alzheimer's disease‐associated SNP." (PMID 41235755, 2025).
attention deficit-hyperactivity disorder (1 paper, 2024). A disorder characterized by a marked pattern of inattention and/or hyperactivity-impulsivity that is inconsistent with developmental level and clearly interferes with functioning in at least two settings (e.g. at home and at school). "Attention deficit hyperactivity disorder (ADHD) was described in 4/104 (PCDH19, CHD2 and MBD5)." (PMID 38279250, 2024).
autoimmune uveitis (1 paper, 2025). An autoimmune form of uveitis (disease). "Cyclosporine, a top predictor, reduced CHD2 expression in fibroblasts with CHASERR knockdown and in murine models of autoimmune uveitis." (PMID 41306969, 2025). "In both our CHASERR knockdown model and in cyclosporine-treated autoimmune uveitis mice, we observed a consistent decrease in CHD2 levels without a corresponding increase in CHASERR expression." (PMID 41306969, 2025).
behavioral disorders (1 paper, 2020). "Another cluster, consisting of three genes (CHD2, SCN10A, and TBC1D8), was associated with cellular assembly and organization, nervous system development and function, and ion channels, as well as neurological disease, skeletal and muscular disorders, and behavioral disorders." (PMID 33584793, 2020).
ependymoma (1 paper, 2016). A WHO grade II, slow growing tumor of children and young adults, usually located intraventricularly. "Poor prognostic features were found in two other patients: low expression of PAX8, FHIT, CASP10, CHD2, with high expression of CHD11, FUS, and MTA1 in a patient with Ewing sarcoma, and gain of 1q and loss of 6q and overexpression of TNC, CALB1, PLAG1, ALDH1L1, and RELN in a patient with ependymoma." (PMID 28007021, 2016).
epileptic seizures (1 paper, 2022). "So far, 144 patients have been reported to have epileptic seizures and associated CHD2 variants." (PMID 35222528, 2022).
generalized epilepsy (1 paper, 2017). Epilepsy that is characterized by generalized seizure types and may have typical interictal and/or ictal EEG findings that accompany generalized seizure types (for example generalized spike-wave). "A de novo nonsense mutation of c.5035 C>T (p.Arg1679X) in CHD2 was found in monozygotic twin girls with generalized epilepsy in the family of D1430." (PMID 28074849, 2017).
glioma (1 paper, 2025). A benign or malignant brain and spinal cord tumor that arises from glial cells (astrocytes, oligodendrocytes, ependymal cells). "RIPK1 was positively correlated with the expression of cyclin E1 (CCNE1), CDK2, TIMP1, N-cadherin (CHD2), and other genes implicated in glioma proliferation and invasion, whereas MLKL exhibited a weaker or negative correlation with most genes in this signature." (PMID 41429922, 2025).
HIV-1 infection (1 paper, 2014). The type species of lentivirus and the etiologic agent of acquired immunodeficiency syndrome (AIDS). "Future studies will provide a more detailed view of the role of CHD1 and CHD2 in the transcription cycle of HIV-1 infection and will further contribute to our understanding of epigenetic regulation of transcription during HIV infection." (PMID 25297984, 2014). "Firstly, an insertional mutagenesis screen identified CHD2 as the disrupted gene in mutant CHO-K1 cells that were resistant to MLV and HIV-1 infection." (PMID 25297984, 2014). "Gain-of-function and loss-of-function experiments performed in human cells confirmed that CHD2 and the highly related CHD1 protein positively regulate MLV and HIV-1 infection." (PMID 25297984, 2014). "Secondly, gain-of-function and loss-of-function experiments in HEK293T cells confirmed that CHD2 and the highly related CHD1 protein positively regulate MLV and HIV-1 infection." (PMID 25297984, 2014). "The siRNAs targeting both CHD-1 and CHD-2 also led to a modest but highly reproducible and statistically significant decrease in HIV-1 reporter gene expression in human SupT1 cells, a T-cell line that is more physiologically relevant for HIV-1 infection." (PMID 25297984, 2014).
Larsen syndrome (1 paper, 2017). A rare skeletal dysplasia characterized by congenital dislocation of large joints, foot deformities, cervical spine dysplasia, scoliosis, spatula-shaped distal phalanges and distinctive craniofacial abnormalities, including cleft palate. "This residue is located within the second calponin homology domain 2 (CHD2) of the filamin B protein, a known hotspot region for Larsen syndrome mutations." (PMID 28639312, 2017).
lymphoma (1 paper, 2020). A malignant (clonal) proliferation of B- lymphocytes or T- lymphocytes which involves the lymph nodes, bone marrow and/or extranodal sites. "Chd2−/− mice display growth delay and perinatal lethality, while heterozygous animals have reduced neonatal viability, shorter life span, and develop lymphomas." (PMID 31900031, 2020). "In addition, the majority of Chd2 heterozygous mutant mice die because of multiple lymphomas and lymphoid hyperplasia, supporting the role of CHD2 in haematologic malignancies." (PMID 31900031, 2020).
memory impairment (1 paper, 2026). "Memory impairments and memory-relevant transcriptional changes observed in Chd2+/- mice are largely recapitulated in both sexes by conditional Chd2+/- in adulthood." (PMID 41872520, 2026).
metastatic tumours (1 paper, 2020). "Other genes, such as BCORL1 (OVA_003), CASP3 (OVA_047), CHD2 (OVA_013), FAT3 (OVA_365) and LZTR1 (OVA_378), were heterogeneous, having differing clonality in the primary versus the metastatic tumours." (PMID 32099096, 2020).
myeloid leukaemia (1 paper, 2020). "Since other CHD family members have been proposed to play a role in pluripotency and myeloid leukaemia, the function of CHD2 in myeloid differentiation was further characterized." (PMID 31900031, 2020).
neurodevelopmental disabilities (1 paper, 2014). "These previous studies, together with our present case series, provide strong evidence that haploinsufficiency of CHD2 is associated with neurodevelopmental disabilities." (PMID 24834135, 2014).
prion disease (1 paper, 2023). A transmissible disease that is caused by a protein that is able to induce abnormal folding of normal cellular proteins, leading to characteristic spongiform brain changes, which are associated with neuronal loss without an inflammatory response. "Among genes associated with prion diseases, the over-expression of some (PSEN1, FYN, SMC3, CHD2, EP300) in late-cycle could be rationalized by considering related proteins in humans, which, when expressed in their monomeric (soluble) form, exert protective functions for cellular homeostasis." (PMID 37048113, 2023).
status epilepticus (1 paper, 2022). Status epilepticus is defined as a continuous seizure lasting more than 30 min, or two or more seizures without full recovery of consciousness between any of them. "They carried a de novo c.5035C>T (p.R 1679*) CHD2 mutation, which has been reported previously.Originally they had status epilepticus, and EEG suggests epileptic discharge, and photosensitivity." (PMID 35386198, 2022).
Stroke (1 paper, 2021). Sudden impairment of blood flow to a part of the brain due to occlusion or rupture of an artery to the brain. "In addition, circ_Dlgap3_1, circ_Tasp1_7, circ_Herc3_2, and circ_Chd2_24 targeted the antiapoptotic protein, Bcl-2, as well as apoptotic protease activating factor 1, supporting their participation in the apoptotic process after stroke." (PMID 34868302, 2021).
uveitis (1 paper, 2025). An inflammatory process affecting a part of or the entire uvea. "In contrast, Chd2 levels were elevated in uveitis but reduced following CsA treatment." (PMID 41306969, 2025).
cancer (10 papers, 2015 to 2025). A tumor composed of atypical neoplastic, often pleomorphic cells that invade other tissues. "CHD 2, 3, 5, and 6 are also associated with DNA repair, the maintenance of genomic stability and/or cancer prevention." (PMID 30043858, 2018). "It has thus been postulated that CHD2 mutation is a driver of cancer, particularly lymphoma." (PMID 33435571, 2021). "Furthermore, CHD2 expression has statistically significant association (p-value 0.029) with the response of cancer cells to CDK inhibitor PD-033299157 which inhibits proliferation." (PMID 27876826, 2016). "These eight transcripts were linked to the following cancer‐related genes: TRIM33, USP6, PRDM16, SETD1B, MLLT3, KEAP1, CHD2, and DCAF12L2." (PMID 32821278, 2020). "CHD1 and CHD2 chromatin remodeling enzymes play important roles in development, cancer and differentiation." (PMID 25621013, 2015). "ACTL6A, CHD2, and ACTB had the highest pan‐cancer G‐score for amplification, whereas CHD5, SHPRH, INO80, and ACTR8 had the highest pan‐cancer G‐score for deletions." (PMID 35789070, 2022).
neurodevelopmental disorder (9 papers, 2014 to 2026). A behavioral and cognitive disorder with onset during the developmental period that involves impaired or aberrant development of intellectual, motor, or social functions. "Mutations in the chromodomain helicase DNA binding protein 2 (CHD2) gene are associated with neurodevelopmental disorders." (PMID 36115870, 2022). "Together, these data describe CHD2 direct targets and mechanisms by which CHD2 prevents precocious hcIN differentiation, which are likely to be disrupted by pathogenic CHD2 mutation to cause neurodevelopmental disorders." (PMID 36115870, 2022). "Subsequently, all patients with reported neurodevelopmental disorder and variants in the CHD2 gene were systematically reviewed and analyzed." (PMID 35222528, 2022). "Although haploinsufficiency of CHD2 is associated with a broad spectrum of neurodevelopmental disorders, we show that variability in the clinical expression of the phenotype can be observed." (PMID 24834135, 2014). "Loss of Chd1 increases seizure susceptibility and disrupts motor function, mirroring phenotypes observed in CHD2-related neurodevelopmental disorders." (PMID 41833011, 2026). "However, most patients with CHD2-related neurodevelopmental disorders remain refractory to treatment." (PMID 35222528, 2022). "Although there is increasing evidence suggesting that mutations in CHD2 contribute to a broad spectrum of neurodevelopmental disorders, a description of the full phenotypic spectrum is lacking." (PMID 24834135, 2014). "In fact, there is emerging evidence suggesting that CHD2 might contribute to a broad spectrum of neurodevelopmental disorders." (PMID 24834135, 2014).
tumor (7 papers, 2014 to 2025). "Chd2 knockout suppressed both tumor initiation and progression, whereas Tnfaip3 knockout enhanced tumor initiation and overall tumor growth." (PMID 41705258, 2025). "The third transcript was associated with CHD2 and CHD4 genes, which play a critical role in tumor suppression, but also in cellular proliferation, senescence, and apoptosis." (PMID 32821278, 2020). "Recent studies have shown that CHD2 protein plays a critical role in embryonic development, tumor suppression and survival." (PMID 24834135, 2014). "All three up-regulated genes (CHD2, TET2, TNFAIP3) were annotated as tumor suppressors." (PMID 30425966, 2018).
neurological disease (6 papers, 2019 to 2025). "We also looked at CHASERR, a highly-conserved lncRNA located near the Chromodomain helicase DNA binding protein 2, a protein associated with a neurological disease." (PMID 38076842, 2025). "Chromodomain helicase DNA binding protein 2 (Chd2) is a chromatin remodeller implicated in neurological disease." (PMID 31704914, 2019).
genetic disorder (3 papers, 2020 to 2024). "Small deletions of the CHD2 locus can cause a rare genetic disorder with growth retardation, cardiac defects and early-natal lethality." (PMID 31900031, 2020). "Our study broadens the geographic scope of CHD2-related phenotypes, providing valuable insights into the prevalence and clinical characteristics of this genetic disorder in previously underrepresented populations." (PMID 39035822, 2024).
infection (2 papers, 2014 to 2019). The state of being infected such as from the introduction of a foreign agent such as serum, vaccine, antigenic substance or organism. "RNAi knockdown of either CHD2 or the related CHD1 protein, in human cells resulted in a block to infection by HIV-1, specifically at the level of transcription." (PMID 25297984, 2014). "Reduced infection in this case was associated with a decrease in CHD1 mRNA levels, as CHD2 mRNA was not depleted in these experiments." (PMID 25297984, 2014).
psychiatric diseases (2 papers, 2020 to 2025). "Furthermore, CHD2 is a master hub node in the AIN with a degree of 34 compared to 12 in the UIN, suggesting altered regulatory interactions in the context of psychiatric disorders." (PMID 40927681, 2025).
CHD2 also shares sentences with these, for which no sentence is quoted: autism spectrum disorder (3 papers); Angelman syndrome (2); Childhood onset (2); generalized tonic-clonic seizure (2); Hirsutism (2); 22q11.2 deletion syndrome (1); Anxiety (1); Ataxia (1); Atypical absence seizure (1); Brain atrophy (1); cerebral small vessel disease (1); channelopathies (1); developmental disabilities (1); diabetic nephropathy (1); early-onset epileptic encephalopathy (1); Ewing sarcoma (1); febrile seizures (1); focal epilepsies (1); Gait ataxia (1); genetic photosensitivity (1); hereditary spastic paraplegia (1); Hirschsprung disease (1); Hypertension (1); infantile spasms (1); Kleefstra syndrome (1); lymph node metastasis (1); Menkes disease (1); Micropenis (1); migraine (1); muscular disorders (1).
A further 13 diseases each share a sentence with CHD2 in 1 paper.